DRC4 (dynein regulatory complex subunit 4)
Description:
Component of the nexin-dynein regulatory complex (N-DRC), a key regulator of ciliary/flagellar motility which maintains the alignment and integrity of the distal axoneme and regulates microtubule sliding in motile axonemes. Plays an important role in the assembly of the N-DRC linker (By similarity). Plays dual roles at both the primary (or non-motile) cilia to regulate hedgehog signaling and in motile cilia to coordinate cilia movement. Required for proper motile cilia functioning. Positively regulates ciliary smoothened (SMO)-dependent Hedgehog (Hh) signaling pathway by facilitating the trafficking of SMO into the cilium and the stimulation of SMO activity in a GRK2-dependent manner (By similarity).
Synonyms: GAS11; GAS8; CILD33
Tractability: Small molecule: a structure with a bound ligand is known. Antibody: its Gene Ontology location is reachable by antibodies, with high confidence; the Human Protein Atlas places it where antibodies can reach. PROTAC: ubiquitination databases record sites on it.
Gene: Protein-coding gene on chromosome 16 (90,019,629 to 90,044,975, forward strand). Ensembl gene ENSG00000141013.
Subcellular location: Cytoplasm; Cytoplasm, cytoskeleton; Cell projection, cilium, flagellum; Cytoplasm, cytoskeleton, cilium axoneme; Cytoplasm, cytoskeleton, cilium basal body; Golgi apparatus; Cell projection, cilium; Cytoplasm, cytoskeleton, flagellum axoneme
Subcellular location (Human Protein Atlas): Cytosol; End piece; Golgi apparatus; Mid piece; Plasma membrane; Primary cilium; Principal piece; Vesicles
Pathways (Reactome):
Signal Transduction: Activation of SMO
Gene Ontology:
Molecular function: protein binding; microtubule binding; small GTPase binding
Biological process: axoneme assembly; cilium movement involved in cell motility; positive regulation of protein localization to cilium; protein localization to cilium; cilium movement; cilium organization; flagellated sperm motility; microtubule cytoskeleton organization; negative regulation of cell population proliferation; positive regulation of smoothened signaling pathway; protein-containing complex assembly; cell motility
Cellular component: axoneme; cilium; Golgi apparatus; microtubule; motile cilium; plasma membrane; sperm end piece; sperm midpiece; sperm principal piece; axonemal nexin link; ciliary basal body; cytoplasm; sperm flagellum; 9+2 motile cilium; cytoskeleton; microtubule cytoskeleton
Genetic constraint (gnomAD): Loss-of-function variants: 65 observed, 56.6 expected, observed/expected ratio (o/e) 1.15, 90% interval 0.94 to 1.41. The upper end of that interval is the gene's LOEUF score, 1.41, which puts it in group 5 of 6, group 1 being the genes least tolerant of losing a copy. Missense variants: 695 observed, 638.56 expected, observed/expected ratio (o/e) 1.09, 90% interval 1.02 to 1.16. Synonymous variants: 264 observed, 252.61 expected, observed/expected ratio (o/e) 1.05, 90% interval 0.94 to 1.16.
Gene-disease validity (ClinGen):
ClinGen rates the evidence that DRC4 causes each of these diseases.
primary ciliary dyskinesia 33 (autosomal recessive): Definitive.
Homologues: Orthologues: macaque GAS8 (98% identical), chimpanzee GAS8 (94% identical), dog GAS8 (93% identical), rabbit GAS8 (92% identical), guinea pig GAS8 (91% identical), rat Gas8 (91% identical), mouse Gas8 (91% identical), pig GAS8 (90% identical), tropical clawed frog gas8 (77% identical), zebrafish gas8 (63% identical), Drosophila melanogaster Gas8 (43% identical).
Diseases named in the same sentence as DRC4 in open-access papers:
DRC4 is named in the same sentence as 28 diseases in open-access papers, as found by Europe PMC text mining. Sharing a sentence is not in itself a finding about the gene and the disease. The quoted sentences say what the papers report.
primary ciliary dyskinesia (4 papers, 2016 to 2025). A rare, genetically heterogeneous, primarily respiratory disorder characterized by chronic upper and lower respiratory tract disease. "Specifically, mutations in DRC1, DRC2/CCDC65, and DRC4/GAS8 are associated with ciliary motility disorders, leading to primary ciliary dyskinesia (PCD)." (PMID 41460250, 2025).
ciliopathies (1 paper, 2023). "In summary, scaffold proteins (DRC1, DRC2, DRC4) play a vital role in assembling the N-DRC since any defect in these subunits can cause severe ciliopathies." (PMID 37714832, 2023).
Infertility (1 paper, 2025). "Similarly, Drc7/Ccdc135 knockout mice display truncated sperm tails and infertility, and mutations in DRC4/GAS8 have been implicated in PCD in humans." (PMID 41460250, 2025).
situs inversus (1 paper, 2025). A congenital condition in which there is complete right-to-left reversal of the position of the major thoracic and abdominal organs (that is, they are arranged in a mirror image of the normal positioning). "As PCD-related genes, Drc1−/−, Drc2−/−, and Drc4−/− mice also exhibited situs inversus, which implicates nodal cilia." (PMID 40089458, 2025). "Additionally, a small percentage of Drc1−/−, Drc2−/− and Drc4−/− mice exhibited situs inversus." (PMID 40089458, 2025).
DRC4 also shares sentences with these, for which no sentence is quoted: breast carcinoma (3 papers); prostate carcinoma (3); tumor (3); bipolar disorder (2); schizophrenia (2); asthma (1); cancer (1); chronic rhinosinusitis (1); cutaneous melanoma (1); cystic kidney disease (1); gastric cancer (1); gastric tumor (1); hepatocellular carcinoma (1); Hydrocephalus (1); liver cancer (1); melanoma (1); Nasal polyposis (1); non-melanoma skin carcinoma (1); oculocutaneous albinism (1); papillary carcinoma (1); Pigmentary retinopathy (1); respiratory infections (1); scarlet fever (1); virus infection (1).